PAX6 (paired box 6)
Diseases named in the same sentence as PAX6 in open-access papers (continued):
Sharing a sentence is not in itself a finding about the gene and the disease.
myopia (continued). "Consistent with a report by others, we were unable to demonstrate an association between PAX6 and myopia." (PMID 17653045, 2007). "For instance, variations in genes such as MYOC and PAX6 have been linked to increased myopia risk." (PMID 39767875, 2024). "PAX6 has recently been identified as a myopia-risk gene by meta-analysis." (PMID 37740201, 2023). "The SNP rs662702 of PAX6 affected the risk of extreme myopia." (PMID 35327754, 2022). "PAX6 locus ophthalmic sequel of mutations located on chromosome 11p13 may be associated with extreme refractive errors, especially high myopia, nystagmus and iris hypoplasia, although the underlying mechanism is not entirely clear." (PMID 35893109, 2022). "One association between myopia at 7 with DNA methylation was near the PAX6 gene." (PMID 31659193, 2019). "We have shown that over-expression of miR-328 is a risk for myopia and PAX6 may have a link with HOXA9, and therefore we tested whether miR-328 can affect HOXA9 expression in both human and mouse RPE cells." (PMID 30674274, 2019). "A recent meta-analysis revealed PAX6 as a risk gene for myopia." (PMID 30674274, 2019). "Although several studies have examined the association between PAX6 and myopia, whether PAX6 is a susceptibility gene for myopia remains controversial." (PMID 23213273, 2012). "Summary of previous reports that evaluated an association between PAX6 and high myopia." (PMID 23213273, 2012). "The association of PAX6 with common myopia was first evaluated in a Caucasian cohort." (PMID 23213273, 2012). "To determine whether PAX6 is associated with high myopia, we conducted a large-cohort case–control study of Japanese participants." (PMID 23213273, 2012). "The objective of this study was to investigate whether genetic variations in the paired box 6 (PAX6) gene are associated with high myopia in Japanese subjects." (PMID 23213273, 2012). "The A allele for rs644242 is protective for high and extreme myopia, and the collaboration of PAX6 and CTNND2 might be associated with the development of this condition." (PMID 23213273, 2012). "Single nucleotide polymorphisms in the PAX6 3′-UTR were associated with myopia in Chinese." (PMID 22550392, 2012). "In addition, an Australian group found rare nonsense PAX6 mutations in family members with high myopia." (PMID 21589860, 2011). "It is therefore possible that variation in the PAX6 expression level may be implicated in influencing the susceptibility to myopia development." (PMID 21589860, 2011). "To attest the association between PAX6 and high myopia, we should look for mutations that may affect PAX6 expressions." (PMID 19907666, 2009). "Two dinucleotide repeats, AC and AG, in the PAX6 P1 promoter were associated with high myopia." (PMID 19907666, 2009). "As insulin is a strong stimulator of axial myopia in chicks, elevated PAX6 expression may increase the risk of developing myopia through increased expression of insulin." (PMID 19907666, 2009). "Moreover, the risk allele could reduce PAX6 protein levels, which may be involved in the underlying mechanism of myopia pathogenesis." (PMID 35327754, 2022). "The researchers investigated the association of the paired box gene 6 (PAX6) with different stages of severity of myopia to confirm whether the PAX6 gene is a genetic determinant only for higher grade myopia, or it has an impact also on a low-grade stage of myopia." (PMID 31781378, 2019). "Although genome-wide linkage scans in a twins study suggested the PAX6 region was strongly linked to common myopia, further case–control studies using tag SNPs rejected the hypothesis of an association between PAX6 and common myopia." (PMID 23213273, 2012). "Still, an Australian study suggested PAX6 mutations might be associated with high myopia." (PMID 19907666, 2009). "Genes like PAX6 and GJD2 are strongly associated with myopia, and studies have shown that children of myopic parents are more likely to develop myopia themselves." (PMID 39854380, 2025).
myopia (continued). "The study involving 506 Caucasian pairs of twins considered PAX6 as a candidate gene for myopia, since it was the closest to the highest linkage peak." (PMID 35327754, 2022). "Pax6 is known to be an important gene for eye development, and research has related miR‐328 to myopia by its binding to the PAX6 locus." (PMID 34841657, 2022). "On the one hand, the results of Metascape revealed a potential role of TF in the development of myopia with the enrichment of Smad6, NrOb2, Gtf2i, Tfap2a, Pax7, Pax6, Sox9 and Smad3." (PMID 34841657, 2022). "Enrichment analysis revealed top eight transcription factors, including PAX6 and Smad3, related to myopia." (PMID 34841657, 2022). "We previously reported that microRNA-328 (miR-328) can bind to PAX6 mRNA and negatively regulate PAX6 expression, which leads to myopia development." (PMID 30674274, 2019). "This admittedly tenuous link to PAX6 is an intriguing addition to the complex story of myopia and its relationship to early brain development." (PMID 30704416, 2019). "Taken together, these findings possibly were in line with a suggestive role played by the PAX6 3′-UTR in myopia etiology." (PMID 22550392, 2012). "Linkage of myopia to the PAX6 region on chromosome 11p13 was shown in several studies, but the results for association between myopia and PAX6 were inconsistent so far." (PMID 21589860, 2011). "We evaluated the influence of (AC)m(AG)n dinucleotide repeats on PAX6 P1 promoter activity by a luciferase-reporter assay and examined the effects of repeat lengths as obtained from our high myopia patients and controls." (PMID 19907666, 2009). "Allelic frequencies of PAX6 P1 promoter grouped dinucleotide repeats, (AC)m and (AG)n, in high myopia (HM) and control subjects." (PMID 19907666, 2009). "The PAX6 gene, located at the reported myopia locus MYP7 on chromosome 11p13, was postulated to be associated with myopia development." (PMID 19907666, 2009). "SNPs were also analyzed in genes where their expression pattern or their association with syndromes conveys myopia as part of the phenotype (FGF2, BDNF, COL2A1, COL18A1, and PAX6)." (PMID 17653045, 2007). "show that an intronic variant in the PAX6 gene is associated with extreme myopia but not with mild myopia." (PMID 36794549, 2023). "A recently published study suggested that in patients with high myopia, PAX6 mutations do not increase the risk of developing myopic maculopathy." (PMID 34065151, 2021). "The PAX6 3′-UTR might be involved in myopia development by regulating the expression of PAX6 mRNAs, which was similar to short repeats in PAX6 promoter." (PMID 22550392, 2012). "Since the expression of the catenin δ2 protein is regulated by transcription factor Pax6 and PAX6 is another myopia-susceptibility gene, PAX6 and CTNND2 might cooperatively affect myopia development." (PMID 23213273, 2012). "Since CTNND2 expression is regulated by Pax6, and that the distribution of Pax6 and δ-catenin/catenin δ2 is remarkably similar, the collaboration of PAX6 and CTNND2 might be associated with myopia." (PMID 23213273, 2012). "Considering the effect of the PAX6 gene, the current inclusion criterion, which is to enroll patients who have two highly myopic eyes, is more suitable for selecting genetic-dependent high myopia." (PMID 23213273, 2012). "This warrants a larger-scale study to clarify the role of PAX6 in myopia." (PMID 21589860, 2011). "The same study and two other studies, however, did not found the association of PAX6 single nucleotide polymorphisms (SNPs) and common myopia." (PMID 21589860, 2011). "The final gene, PAX6, has been positively associated with high grade myopia in two independent studies, but results have been negative for common myopia." (PMID 19365569, 2009). "We found no myopia mutations in the coding regions and splice sites in PAX6 in our cohort of Chinese high myopia patients." (PMID 19907666, 2009). "miR-328 may influence myopia development by mediating the PAX6 gene." (PMID 39403500, 2024).
myopia (continued). "Researchers indicate that PAX6 rs644242, ZC3H11B rs4373767 and BICC1 rs7084402, VIPR2 rs885863 and rs6979985, ZMAT4 rs7829127, TNKS rs4840437 and rs6989782, PDGFRA rs2114039, SOX2 rs4575941, FGF10 rs339501, rs2973644, and rs 79002828 are associated with severe myopia (moderate and extreme myopia)." (PMID 38660258, 2024). "Moreover, the rs644242 SNP on the PAX6 gene was associated with extreme myopia but not lower-grade myopia." (PMID 35327754, 2022). "It seems that PAX6 is more likely a susceptibility gene for high myopia, rather than common myopia." (PMID 21589860, 2011). "Although Pax6 also transactivates the glucagon promoter, which is a “stop” for myopia, insulin might overcome the effects of glucagon in the development of myopia." (PMID 19907666, 2009). "Lack of informative families for two of the PAX6 SNPs made the association between myopia and these SNPs unknown." (PMID 17653045, 2007). "However, although PAX6 has been postulated to be a candidate gene for myopia, several studies in Caucasian populations could not find an association between PAX6 and myopia." (PMID 19907666, 2009). "The PAX6 gene at this locus, a member of the paired-domain PAX family, has been postulated as a candidate gene for myopia." (PMID 19907666, 2009). "The methylation level of the PAX6 gene in the myopic group of junior high school students was slightly higher than that in the non-myopic team, and the more severe the myopia, the lower the level of the methylation PAX6 gene." (PMID 40657400, 2025). "Hence, to date, PAX6, HGF, and UMODL1 remain the strongest candidates for high grade myopia and collagen, type 2, alpha 1 (COL2A1) for common myopia." (PMID 19365569, 2009). "Others were chosen for their potential biological relevance to myopia (FGF2, BDNF, and PAX6)." (PMID 17653045, 2007). "They found that PAX6 is a genetic determinant for extreme myopia rather than lower grade myopia, suggesting that PAX6 could be involved in the development or progression into severe myopia, but could not impact the myopia onset." (PMID 31781378, 2019). "Moreover, patients with myopia had a higher level of miR-328 expression compared to healthy controls, but the expression level was not related to the genotype of the 3′UTR of the PAX6 gene." (PMID 39597899, 2024).
Anophthalmia (32 papers, 2007 to 2025). Absence of the globe or eyeball. "Anophthalmia is associated with homozygous PAX6 variants, where there is biallelic loss of function." (PMID 32111086, 2020). "There are significant overlaps with anophthalmia (e.g. mutation in Pax6, Bmp4, Bmp7) as well as with cataracts (e.g. mutations affecting genes coding for crystallins or connexins)." (PMID 30919050, 2019). "Specifically, the presence of one defective copy of PAX6 results in ocular malformations, but mutations in both copies of PAX6 cause ocular phenotypes that are more severe (e.g., anophthalmia) and brain abnormalities that are incompatible with life." (PMID 29850208, 2018). "Although PAX6 mutations are an extremely rare cause of anophthalmia, there has recently been interest in a possible co-operative role between PAX6 and SOX2." (PMID 18039390, 2007). "In humans, heterozygous loss-of-function mutations typically produce aniridia (OMIM 106210), a congenital panocular malformation associated with severe visual impairment; however PAX6 was also the first gene implicated in human anophthalmia." (PMID 18039390, 2007). "Deletion of Pax6 resulted in embryonic lethality and anophthalmia in homozygous (HOM) embryos, and 16-week-old Pax6 heterozygous (HET) animals had multiple congenital defects including a central corneal defect with persistent lenticular involvement." (PMID 39833678, 2025). "Conversely, Pax6 haploinsufficiency in mice results in the Small eye and cataract phenotypes, and nullizygosity results in a failure of lens placode induction and anophthalmia." (PMID 25517354, 2014). "Anophthalmia can occur as a unique clinical feature, although in one-third of cases it is associated to genetic syndromes, such as the Wolf-Hirschhorn or mutations of the SOX2 or PAX6 genes." (PMID 28673238, 2017). "Pax6 is widely expressed during normal eye development, however, absence of Pax6 causes anophthalmia in mice and humans." (PMID 27463523, 2016). "The anophthalmia and early lethality of Pax6−/− homozygous mean that this genotype is only useful for early developmental stages unless used in mouse chimaeras and the Pax6+/− genotype has only minor effects in tissues other than the eye." (PMID 27240603, 2016). "Interestingly, expression of a stabilised β-catenin isoform under the control of Pax6 enhancer elements confers severity on lens development across littermates, which is reminiscent of the anophthalmia variability across in the WNT inhibitor-rescued Apcmin/flox pups." (PMID 37893093, 2023). "The classical paradigm for anophthalmia in the mouse, however, is the homozygous Pax6 mutants (paired box 6), which do not develop eyes in homozygous mutants." (PMID 30919050, 2019). "Pax-6 homozygous mutants, the classical model for anophthalmia in the mouse, do not develop eyes, but die perinatally because of other developmental defects, including those of the central nervous system." (PMID 31817535, 2019).
glaucoma (30 papers, 2012 to 2025). Increased pressure in the eyeball due to obstruction of the outflow of aqueous humor. "Interestingly, PAX6 has previously been associated with glaucoma and FOSL1, which is associated with fibrosis, were both previously identified in an earlier study exploring the effect of αvβ3 integrin on the transcriptome of TM cells." (PMID 38394161, 2024). "For PAX6 and FOXC1, this is consistent with their broad expression patterns in the eye and the phenotypic heterogeneity and overlap linked to FOXC1 and PAX6 mutations, e.g., iris and corneal defects and higher prevalence of glaucoma, reinforcing a common regulatory network shared by the 2 TFs." (PMID 37856539, 2023). "Natural history of glaucoma in patients with PAX6 mutations." (PMID 34101622, 2021). "For instance, PAX6 and LMX1B are both associated with ASD which, in turn, is associated with an increased risk of glaucoma." (PMID 34440692, 2021). "Exclusion of pathogenic variations in known glaucoma genes as CYP1B1, MYOC, FOXC1, PITX2 and PAX6 was additionally done per Sanger sequencing and Multiple Ligation-dependent Probe Amplification (MLPA) analysis." (PMID 27484908, 2016). "In conclusion, we exhibited a possible surgical approach to manage PAX6 aniridic glaucoma." (PMID 38594720, 2024).
Nystagmus (30 papers, 2006 to 2025). Rhythmic, involuntary oscillations of one or both eyes related to abnormality in fixation, conjugate gaze, or vestibular mechanisms. "Recently, a phenotype characterized by isolated foveal hypoplasia with nystagmus has been also linked to PAX6 variation." (PMID 38383453, 2024). "The mutation or deletion of ELP4 can suppress the expression PAX6 which controls eye development, and results in aniridia syndrome characterized by impaired vision and nystagmus." (PMID 35456484, 2022). "In this study, we report two independent families presenting with isolated foveal hypoplasia and nystagmus caused by missense heterozygous changes in PAX6 predicted to affect the PD." (PMID 33024313, 2021). "Clinicians should be aware that mutations in the PAX6 gene can initially present as bilateral congenital cataracts and search for the mutation, especially if the patient has low vision, nystagmus, and foveal hypoplasia." (PMID 34065151, 2021). "The function of the PAX6 protein is crucial in human eye development, and patients affected with PAX6 mutations showed a wide variety of congenital ocular disorders, often resulting in nystagmus and severe visual impairment." (PMID 34065151, 2021). "We report two families with isolated foveal hypoplasia and nystagmus (OMIM 136520) caused by two different PAX6 missense variants predicted to affect the PD." (PMID 33024313, 2021). "Isolated foveal hypoplasia, which is usually accompanied by nystagmus, has been described in few families with PAX6 missense mutations in the paired domain: c.227C>G, p.Pro76Arg and c.382C>T, p.Arg128Cys." (PMID 31861090, 2019). "In summary, this study added a novel missense mutation to the existing spectrum of PAX6 mutations in a Chinese family with nystagmus, cataract and iris anomalies." (PMID 22025896, 2011). "In this study, mutation analysis of PAX6 was performed in a large Chinese family with nystagmus, cataract, and iris anomalies." (PMID 22025896, 2011). "This work contributes to increase the phenotypic spectrum caused by PAX6 variants, and to our knowledge, is the first report to describe the presence of postzygotic parental mosaicism causing isolated foveal hypoplasia with nystagmus." (PMID 33024313, 2021). "Moreover, it is also unlikely that our patients had PAX6 mutations, since, as we have shown, in patients with PAX6 mutations the nystagmus form is very different, usually with a vertical component." (PMID 24688117, 2014). "Although the patient had congenital cataract, he also had additional features that included ptosis, trans-illumination defects of the iris, reduced visual acuity and nystagmus, therefore a diagnosis of PAX6-related phenotype was considered." (PMID 28378818, 2017). "PAX6 c.221G>A and WFS1 c.2070_2079del were novel heterozygous mutations that are associated with severe congenital cataract even causing blindness in childhood with nystagmus." (PMID 36843716, 2023). "A recent analysis of 15 patients with deletions in the PAX6 3′ regulatory region showed significantly milder phenotypes compared with all other mutations, with no reported nystagmus, ARK, or foveal hypoplasia." (PMID 34101622, 2021). "In this study, we analyzed PAX6 in a Chinese pedigree of nystagmus, cataract and iris anomalies." (PMID 22025896, 2011).